LMNA (lamin A/C)
Diseases named in the same sentence as LMNA in open-access papers (continued):
Sharing a sentence is not in itself a finding about the gene and the disease.
laminopathies (continued). "This suggests that ECM alterations, triggered by several LMNA mutations in different tissues, could globally contribute to the pathophysiology of laminopathies, and that antagonists of TGF-beta may have potential therapeutic benefit in these diseases." (PMID 29578370, 2018). "Laminopathies are a heterogeneous group of diseases, caused by mutations in lamin A/C proteins." (PMID 29895224, 2018). "LMNA mutations cause a plethora of diseases called laminopathies, of which three forms affect skeletal muscle: limb-girdle muscular dystrophy type 1B (LGMD1B), autosomal dominant Emery-Dreifuss muscular dystrophy 2 (EDMD2), and LMNA-related congenital muscular dystrophy (L-CMD)." (PMID 29669293, 2018). "Additionally, it has been recently published that everolimus is also improving the phenotype in fibroblast cell lines from six laminopathy patients with different LMNA mutations." (PMID 30425656, 2018). "As many structural and regulatory roles of A-type lamins are impaired by LMNA mutations, the pathophysiological mechanisms of the different laminopathies could involve distinct pathways." (PMID 29578370, 2018). "Mutations in the LMNA gene encoding A-type lamins cause a wide range of diseases, including muscular dystrophies, lipodystrophy, and progeria, which are collectively referred to as laminopathies." (PMID 28134781, 2017). "Furthermore, mutations in the gene encoding A-type lamins (LMNA) have been associated with at least 8 different diseases collectively termed laminopathies, including Hutchinson Gilford Progeria syndrome and Emery Dreifuss Muscular Dystrophy." (PMID 28152338, 2017). "For instance, we only assessed LMNA missense variants represented in ExAC, the laminopathy database and Type 2 Diabetes Knowledge Portal, and hence excluded information that may be available in other web-based or literature-based sources." (PMID 28663758, 2017). "Mutations in LMNA cause laminopathies which affect specific tissues through still largely unknown mechanisms." (PMID 28137286, 2017). "As another example, mandibuloacral dysplasia type A is caused by a recessive mutation of the LMNA gene and is a rare laminopathy characterized by several skeletal and tissue defects, including postnatal growth retardation, craniofacial anomalies, and bone resorption at specific sites." (PMID 28134781, 2017). "It is also tempting to speculate that an impairment of lamin's chromatin-regulating functions in the diseases linked to LMNA mutations (laminopathies) may contribute to the disease phenotype." (PMID 26798136, 2016). "Mutations on the LMNA gene very often are the cause of cardiac compromise, which can occur isolated or be associated with disorders affecting other tissues in the context of laminopathies." (PMID 27529282, 2016). "Mutations in the LMNA gene cause a series of rare and diverse diseases called laminopathies." (PMID 26098624, 2015). "Mutations of the lamin A/C gene have been associated with several diseases such as Emery-Dreifuss muscular dystrophy, dilated cardiomyopathy and Charcot-Marie-Tooth disease, referred to as laminopathies." (PMID 25886484, 2015). "Both are laminopathies, diseases associated with mutations in the LMNA gene." (PMID 24305605, 2014). "The pathogenic mechanism underlying the association between the LMNA mutations and laminopathies remains unclear." (PMID 24349489, 2013). "Laminopathies are mainly attributed to mutations in the LMNA gene." (PMID 23138638, 2013). "More than 450 different mutations have been identified in the LMNA gene that can cause a variety of diseases, called laminopathies, and have been categorized into 4 major types of disorders: striated and cardiac muscle diseases, lipodystrophy syndromes, peripheral neuropathy and premature aging." (PMID 24349489, 2013).
laminopathies (continued). "Laminopathies, due to mutations in LMNA, encoding A type-lamins, can lead to premature ageing and/or lipodystrophic syndromes, showing that these diseases could have close physiopathological relationships." (PMID 23849162, 2013). "To date, more than 237 LMNA mutations, leading to at least 163 protein variants, are known to be associated with at least 10 different degenerative disorders, collectively referred to as laminopathy." (PMID 22709970, 2012). "In this respect, development of methods of increasing expression of wild-type LMNA may offer a means of treating both laminopathies and other human diseases association with genetic variation at this locus." (PMID 23090008, 2012). "LMNA mutations in humans cause a wide range of phenotypes, collectively termed laminopathies." (PMID 20376364, 2010). "Mutations in LMNA directly affect the nuclear morphology as observed in human laminopathies." (PMID 19849840, 2009). "In addition to the laminopathies caused by loss-of-function mutations, disease and changes in cultured cells are associated with overexpression of both LMNA and LMNB1." (PMID 17565385, 2007). "We selected lmn-1 mutations that are homologous to LMNA missense variants reported in striated muscle laminopathy patients and classified them based on whether they were known to exhibit cardiac defects only (DCM-CD), or both cardiac and skeletal muscle defects (AD-EDMD)." (PMID 37624850, 2023). "In fact, any mutation in the LMNA sequence aimed at impairing prelamin A processing may either lead to expression of a pathogenetic prelamin A mutant (as in the case of LMNA L647R, which is associated with a progeroid laminopathy) or cause toxic levels of prelamin A." (PMID 36467410, 2022). "Thus, MADA is a laminopathy caused by homozygous and compound heterozygous LMNA mutations." (PMID 34680903, 2021). "Thus, these few main examples of laminopathies demonstrate that mutations in the same LMNA gene could lead to the development of severe abnormalities, characterized by a wide range of clinical tissue-specific phenotypes." (PMID 34722546, 2021). "However, it is interesting that cluster analysis of LMNA mutations gives preference to one or another hypothesis depending on the localization of LMNA mutations associated with a particular type of laminopathies." (PMID 34722546, 2021). "Interestingly, laminopathies seem to be under-diagnosed, as a study analyzing metabolic syndrome reported that 10% of patients presented abnormal nuclear envelope and 3.6% possessed a mutation in the Lamin A (LMNA) gene." (PMID 34298904, 2021). "Mandibuloacral dysplasia (MADA; OMIM, 248370) is a laminopathy that is characterized by lipodistrophy, skeletal abnormalities, metabolic alterations, and postnatal growth retardation, and it is due to mutations in LMNA that are responsible for the accumulation of the lamin A precursor." (PMID 32481609, 2020). "However, the rationale behind LMNA mutations and laminopathies continues to elude scientists." (PMID 32453974, 2020). "LMNA encodes the nuclear membrane proteins Lamin A and Lamin C, and pathological variants are known to cause a broad variety of inherited diseases referred to as laminopathies, including myopathies in skeletal muscle with a dystrophy-like picture, cardiomyopathy, and conduction system disease." (PMID 31552271, 2019). "Expression of a variety of EDMD and DCM LMNA variants in fruit fly resulted in a host of nuclear aberrations such as lamin-C aggregates and/or increased nuclear blebbing, which are similar to what were previously observed in transfected cells expressing striated muscle laminopathy mutations." (PMID 30934932, 2019). "To assess the prevalence of LMNA missense mutations (‘variants’) in a broad, ethnically diverse population, we compared missense alleles found among 60,706 unrelated individuals in the ExAC cohort to those identified in 1,404 individuals in the laminopathy database (UMD-LMNA)." (PMID 28663758, 2017).
laminopathies (continued). "Finally, beyond their application in HGPS, the effect of RAs on lamin A and lamin C also highlights the potential use of these compounds as treatment for hundreds of other diseases caused by other mutations in the LMNA gene, grouped under the term of laminopathies." (PMID 27739443, 2016). "Although there are many laminopathy phenotypes, some mutations appear to have strong phenotype–genotype correlation in LMNA-related muscular dystrophy and would guide further mechanistic studies of the pathogenesis of skeletal- and cardiac muscle–specific involvement in LMNA mutations." (PMID 26098624, 2015). "Notably, lethal neonatal laminopathies have now been identified and are caused by some specific mutations in the LMNA and ZMPSTE24/FACE-1 genes, suggesting that certain developmental abnormalities may be involved in some cases." (PMID 21479207, 2011). "Therefore, one possible contributing mechanism for the phenotypic variability in laminopathies could be the existence of low and high expressing alleles in the LMNA locus." (PMID 21980471, 2011). "Implicating a role for SUN1 in aging, SUN1 overaccumulation is a common finding in mouse models of laminopathies and premature aging (i.e. LMNA-/-, LMNAΔ9)." (PMID 39827403, 2025). "Our case expands the clinical spectrum of LMNA p.Asp300Asn and underscores the importance of considering laminopathies in patients with unexplained early-onset cardiac disease." (PMID 41300702, 2025). "Nuclear shape anomalies have been associated with laminopathies like the Hutchinson Gilford progeria syndrome (HGPS), which is genetically caused by mutations in the Lamin A/C gene (LMNA) and results in accelerated ageing of affected patients." (PMID 39191852, 2024). "As the most common form of laminopathy, Hutchinson Gilford progeria syndrome (HGPS) is caused by an autosomal dominant mutation in LMNA, the gene encoding for lamin A and C proteins." (PMID 37013265, 2023). "A wide range of mutations to the LMNA gene, as well as a more limited set of mutations to the LMNB1 and LMNB2 genes, cause a phenotypically diverse group of “laminopathy” syndromes." (PMID 37619289, 2023). "One subtype of laminopathy is the generalized lipodystrophy-associated progeroid syndrome (GLPS), which occurs in patients with heterozygous mutations of the LMNA gene c.29C>T(p.T10I)." (PMID 37448194, 2023). "We determined that the Lamin A/C proteins have significantly longer lifetimes within the cardiovascular system and fat, which are disrupted in laminopathies, while these proteins have shorter lifetimes in disease-spared tissues such as the liver and intestine." (PMID 37162946, 2023). "The findings, along with the data in cardiac myocyte-specific models of laminopathies, denote activation of the DDR pathway as a cell-autonomous pathogenic consequence of LMNA deficiency in the heart." (PMID 35891706, 2022). "Mutations in the LMNA gene cause a diverse array of clinical phenotypes, in addition to DCM, which are collectively referred to as laminopathies." (PMID 35891706, 2022). "In accord with the ubiquitous expression of the LMNA gene in various cell types, the phenotypes in laminopathies are the aggregate consequences of the expression of the causal mutations in multiple cell types, tissues, and organs." (PMID 35891706, 2022). "The role of LMNA in osteogenesis has attracted attention, since it plays a significant role in laminopathies." (PMID 34944031, 2021). "A total of 90% of known laminopathies relate to the LMNA gene, and only two diseases are reported to be linked to mutations in LMNB1 or LMNB2 genes: the autosomal-dominant leukodystrophy and Barraquer-Simons syndrome, respectively." (PMID 32456328, 2020). "Overall, the data showed that PKC-α localization, activation, and proximity with lamin A/C were affected by certain pathogenic LMNA mutations, suggesting PKC-α involvement in striated muscle laminopathies." (PMID 33142761, 2020).
laminopathies (continued). "In contrast, there is aberrant upregulation of ERK/MAPK pathway in affected tissues such as LMNA mutant cardiomyocytes which leads to laminopathy phenotype." (PMID 32698886, 2020). "The majority of laminopathies map to the LMNA gene with a strong prevalence of autosomal dominant missense mutations." (PMID 31266244, 2019). "Mandibulo-acral dysplasia, due to mutations in LMNA or ZMPSTE24, was identified as the first laminopathy associating premature ageing and lipodystrophic features." (PMID 29578370, 2018). "In this study, three LMNA-mutant iPSC lines K32del, R249W, and L35P from patients affected by skeletal muscle laminopathies have successfully been differentiated into inducible skeletal myogenic cells and then into terminally differentiated myotubes in vitro." (PMID 30405424, 2018). "Lamin A/C, encoded by LMNA gene, which is associated with subgroup of envelopathies called laminopathies, is a main component of nuclear lamina, located under the inner nuclear membrane, but in a smaller amount it is also found in the nucleoplasm." (PMID 29633897, 2018). "Here, we review current knowledge on laminopathies affecting bone and LMNA involvement in bone turnover and highlight lamin-dependent mechanisms causing bone disorders." (PMID 29854317, 2018). "One of the most severe laminopathies, Hutchinson Gilford Progeria Syndrome (HGPS), is caused by a de novo single-base substitution in the exon 11 of LMNA gene." (PMID 29637811, 2018). "It has been reported that LMNA mutation activates AKT mTOR signaling and impairs autophagy, which results in cell damage that causes laminopathies, and down-regulation of the LMNA gene in neuroblastoma promotes tumor progression." (PMID 30460069, 2017). "Of note, rapamycin has been shown to reverse elevated mTORC1 signaling in lamin A/C-deficient mice, showing that a direct effect of the drug on the m-TOR pathway is beneficial not only in progeroid, but even in muscle laminopathies." (PMID 25324471, 2014). "Although, two animal models of lamin A/C knockout differ in severity of phenotype, together with many mice laminopathy models, they provide the same message, that lamins and lamina-associated proteins affect myogenesis and muscle regeneration." (PMID 23138638, 2013). "Increasing numbers of mutations in LMNA, ZMPSTE24 or genes encoding lamin partners have been associated with tissue-restricted or systemic disorders collectively termed “laminopathies”." (PMID 23285253, 2012). "We describe the induction of embryonic senescence and laminopathies in zebrafish harboring disturbed expressions of the lamin A gene (LMNA)." (PMID 21479207, 2011). "An exemplar of laminopathy/envelopathy is Emery-Dreifuss muscular dystrophy (EDMD), which is autosomal dominant when caused by mutations in LMNA, whereas it is X-linked when caused by changes in the NL-associated protein, emerin." (PMID 20376364, 2010). "Laminopathies exhibit ERK pathway hyperactivation, observed in LMNA mutations causing cardiomyopathy or SMAD6 overexpression, accelerating myogenic differentiation in LMNA-mutated cells." (PMID 38566066, 2024). "To further validate this finding, we tested whether sarcomere abnormalities were also present in LMNA mutant human myotubes from striated muscle laminopathies." (PMID 34433058, 2021). "Although not widely recognized as a form of laminopathy, several studies have documented the occurrence of kidney-related diseases in patients with LMNA mutation-induced lipodystrophy or DCM." (PMID 34246298, 2021).
laminopathies (continued). "In contrast, Ser458 was not phosphorylated in neuromuscular disorders unrelated to LMNA mutations or cells expressing mutant Lamin A that causes non-myopathic laminopathies." (PMID 33030403, 2020). "Another axis to explore includes the mechanobiological processes in which the lamin A/C protein is central and the processes that could be involved in the development of laminopathy phenotypes." (PMID 32842478, 2020). "However, anomalous prelamin A accumulation, due to specific mutations in the LMNA or ZMPSTE24 genes, causes toxicity leading to cellular senescence and represents the molecular basis of progeroid laminopathies." (PMID 31428229, 2019). "In skeletal muscle, morphological abnormalities were classified as enlarged, elongated, wrinkled, and deformed nuclei, which were also observed in both skeletal muscle from laminopathy patients and LMNA-mutant human induced pluripotent stem cell-derived inducible myogenic cells." (PMID 31430335, 2019). "Nevertheless, impaired HDAC2 recruitment to the lamin A/C‐containing platform occurs irrespective of the mutated LMNA sequence, a finding that suggests involvement of other molecular defects common to progeroid laminopathies, such as prelamin A accumulation." (PMID 30109767, 2018). "Since Lamin A/C covers such a variety of roles, it is not surprising that mutations in the LMNA gene cause a wide set of pathologies, grouped all together under the term of Laminopathies." (PMID 29619865, 2018). "The roles of LMNA on chromatin organization and mobility suggest that laminopathies may involve altered interactions of LMNA with chromatin in distinct nuclear compartments." (PMID 28137286, 2017). "Mutations in the LMNA gene, encoding the nuclear intermediate filament proteins lamin A/C, account for 6% of familial DCM patients in addition to causing a wide spectrum of diseases, named laminopathies." (PMID 28398466, 2017). "This study isolated novel genes and functions potentially involved in LMNA network of regulation that could be involved in laminopathies such as the Hutchinson-Gilford progeria syndrome." (PMID 23317481, 2013). "Thus, antibodies specifically recognizing mutant lamin A/C proteins would be highly valuable research tools to study the molecular mechanisms of laminopathies in primary human patient cells and tissues." (PMID 20498701, 2010). "The pathogenesis of DCM with conduction system abnormalities in laminopathies is likely multifaceted and includes disrupted chromatin modelling, abnormal activation of mitogen-activated protein kinase (MAPK) and TGF-β-related pathways, and altered calcium loading related to LMNA variants." (PMID 39204134, 2024). "Thus, we established C. elegans avatars for striated muscle laminopathies and identified LMNA variants that offer insight into lamin mechanisms during normal development." (PMID 37624850, 2023). "Therefore, the effect of the c.784G>A mutation in the LMNA gene on laminopathy‐associated progeroid manifestation is not related to the formation of alternative isoforms of LMNA nor to the differences in the expression of LMNAE262K and LMNA." (PMID 36225129, 2022). "Whereas most studies have been focused on lamin A/C’s function in preventing skeletal muscle dystrophy, few reports are available regarding the relationship between laminopathies and osteoporosis and whether and how lamin A/C regulates bone mass homeostasis and prevents osteoporosis." (PMID 32479501, 2020). "Importantly, treatment with rapamycin, which is a specific mTOR-inhibitor, contributed to an improvement of LMNA–/– mice phenotypes and an elevation of survival, showing that mTOR activation might mediate phenotypes involved in laminopathy diseases." (PMID 32842478, 2020). "Differential expression patterns of A- and B-type lamins may explain the tissue-specific pathology that occurs in many laminopathies, for example, the absence of dementia in Hutchinson-Gilford progeria patients, which is caused by mutations in LMNA." (PMID 31225490, 2018).